ZSCAN29 (zinc finger and SCAN domain containing 29)
Description:
May be involved in transcriptional regulation.
Synonyms: ZNF690; FLJ35867; Zfp690
Tractability: Antibody: the Human Protein Atlas places it where antibodies can reach. PROTAC: UniProt records ubiquitination sites on it; ubiquitination databases record sites on it.
Gene: Protein-coding gene on chromosome 15 (43,357,920 to 43,371,048, reverse strand). Ensembl gene ENSG00000140265.
Subcellular location: Nucleus
Subcellular location (Human Protein Atlas): Nucleoplasm; Actin filaments; Plasma membrane
Gene Ontology:
Molecular function: sequence-specific double-stranded DNA binding; DNA-binding transcription factor activity, RNA polymerase II-specific; RNA polymerase II cis-regulatory region sequence-specific DNA binding
Biological process: regulation of transcription by RNA polymerase II
Cellular component: nucleus
Genetic constraint (gnomAD): Loss-of-function variants: 57 observed, 77.11 expected, observed/expected ratio (o/e) 0.74, 90% interval 0.6 to 0.92. The upper end of that interval is the gene's LOEUF score, 0.92, which puts it in group 3 of 6, group 1 being the genes least tolerant of losing a copy. Missense variants: 1,042 observed, 1,097.3 expected, observed/expected ratio (o/e) 0.95, 90% interval 0.9 to 1. Synonymous variants: 351 observed, 391.35 expected, observed/expected ratio (o/e) 0.9, 90% interval 0.82 to 0.98.
Homologues: Orthologues: chimpanzee ZSCAN29 (99% identical), macaque ZSCAN29 (95% identical), dog ZSCAN29 (88% identical), rabbit ZSCAN29 (87% identical), guinea pig ZSCAN29 (84% identical), mouse Zscan29 (81% identical), pig ZSCAN29 (60% identical), Drosophila melanogaster CG12391 (9% identical), Drosophila melanogaster hb (8% identical), zebrafish plagl2 (8% identical), zebrafish ovol1a (7% identical), zebrafish ovol1b (7% identical), and 4 more. Paralogues in human: ZKSCAN2 (52% identical), ZSCAN32 (35% identical), ZNF202 (22% identical), ZNF18 (22% identical), ZNF496 (19% identical), ZNF274 (17% identical), ZNF174 (16% identical), ZSCAN5C (15% identical), ZSCAN5B (15% identical), ZSCAN5A (15% identical), ZNF446 (14% identical), ZSCAN18 (13% identical), and 17 more.
Diseases named in the same sentence as ZSCAN29 in open-access papers:
ZSCAN29 is named in the same sentence as 1 disease in open-access papers, as found by Europe PMC text mining. Sharing a sentence is not in itself a finding about the gene and the disease.
ZSCAN29 shares sentences with these, for which no sentence is quoted: lung carcinoma (1 paper).